RHOB (ras homolog family member B)
Diseases named in the same sentence as RHOB in open-access papers (continued):
Sharing a sentence is not in itself a finding about the gene and the disease.
inflammation (1 paper, 2022). Aberrant reaction of the microcirculation characterized by movement of fluid and leukocytes from the blood into extravascular tissues. "It has been shown that in human lung inflammation, miR-223 can alleviate the inflammation caused by the release of inflammatory factors in the lung by directly targeting the 3′ UTR of RHOB, and low expression of RHOB has been closely associated with a lack of NF-κB signaling pathway activity." (PMID 36231106, 2022).
retinopathy (1 paper, 2019). "Excitingly, an antibody against RhoB decreases angiogenesis in a model of proliferative retina angiogenesis and oxygen-induced retinopathy in an early pre-clinical study, suggesting that RhoB may not be required for vessel maintenance and could be specific to pathogenic vessels." (PMID 31174284, 2019).
RHOB also shares sentences with these, for which no sentence is quoted: invasive carcinoma (3 papers); schizophrenia (3); ulcerative colitis (3); Dyslipidemia (2); endometriosis (2); multiple myeloma (2); Sepsis (2); Alzheimer disease (1); anaplastic astrocytoma (1); Anxiety (1); astrocytomas (1); cerebral palsy (1); chronic kidney disease (1); epilepsy (1); follicular thyroid carcinoma (1); gastric adenocarcinoma (1); HCMV infection (1); Hypertension (1); Infertility (1); inflammatory bowel disease (1); interstitial lung disease (1); ischemic stroke (1); knee osteoarthritis (1); lung neoplasm (1); lung squamous cell carcinoma (1); myasthenia gravis (1); ovarian clear cell cancer (1); pancreas (1); pancreas carcinomas (1); papillary thyroid carcinoma (1).
A further 6 diseases each share a sentence with RHOB in 1 paper.